G6PD (glucose-6-phosphate dehydrogenase)
Diseases named in the same sentence as G6PD in open-access papers (continued):
Sharing a sentence is not in itself a finding about the gene and the disease.
Myalgia (1 paper, 2019). "There are reports in the literature that come from case studies with no rigid research designs, which report that heavy exercise in G6PD-deficient individuals caused clinical signs of haemolysis, muscle degeneration, myalgia, and myoglobinuria, which may be attributed to increased oxidative stress." (PMID 31089417, 2019).
neurofibroma (1 paper, 2025). An intraneural or extraneural neoplasm arising from nerve tissues and neural sheaths. "Patient MPNST samples showed transcriptional up-regulation of the NRF2/G6PD axis relative to benign precursor lesions, neurofibromas." (PMID 40802750, 2025).
non-alcoholic steatohepatitis (1 paper, 2025). "This state is reminiscent to non-alcoholic steatohepatitis (NASH) because of the downregulation of PPARα-related lipid metabolism and inhibition of glycogenesis (GYS2 down), which suggests glucose release or glycolysis (G6P and G6PC3 up, G6PD down)." (PMID 40806595, 2025).
ovarian tumors (1 paper, 2022). "Our proteomics data also revealed expression of G6PD to be higher in the OVCAR5 CBPR cells and this was consistent in platinum-resistant human ovarian tumors compared to their chemo-sensitive counterparts." (PMID 36463238, 2022). "An enhanced expression of EMT and metabolism regulators including G6PD and AKR1B1 and TGFβ1 observed in vitro in carboplatin resistant cell line was confirmed in platinum resistant and relapsed human ovarian tumor samples, compared to chemo naïve human tumors." (PMID 36463238, 2022).
plexiform neurofibroma (1 paper, 2025). An elongated and multinodular neurofibroma, formed when the tumor involves either multiple trunks of a plexus or multiple fascicles of a large nerve, such as the sciatic. "Together, these results demonstrate activation of the NRF2/G6PD axis in MPNST development and identify a critical metabolic adaptation that MPNSTs undergo in transformation from a plexiform neurofibroma to an MPNST." (PMID 40802750, 2025).
pneumococcal bacteremia (1 paper, 2020). "Dividing the study period into pre-decline (pre-2000), decline (2000–2006), and post-decline (post-2006) periods, we fitted multinomial regression models of pneumococcal bacteremia risk secondary to G6PD status, considering each time period as a stratum." (PMID 32536341, 2020). "Under an additive model, the data provide support for a model in which decreasing G6PD activity (estimated by rs1050828 genotype) only increased the risk of pneumococcal bacteremia during the pre-decline period (ORPre-decline = 1.41, 95% CI 1.01–1.97, PPre-decline = 0.044)." (PMID 32536341, 2020). "To investigate whether G6PD status is a determinant of pneumococcal bacteremia risk, we tested for association between the rs1050828 locus and pneumococcal bacteremia." (PMID 32536341, 2020). "We did not see any protective effect of heterozygosity at G6PD on pneumococcal bacteremia risk." (PMID 32536341, 2020).
Progressive myoclonic epilepsy (1 paper, 2024). "In addition, it has been indicated that G6PD deficiency may be a predisposing factor for rhabdomyolysis following a tonic–clonic seizure and progressive myoclonic epilepsy can be associated with a mutation in G6PD." (PMID 38339211, 2024).
proliferative diabetic retinopathy (1 paper, 2022). Advanced retinopathy due to diabetes mellitus characterized by the formation of new vessels in the retina. "Proliferative diabetic retinopathy only occurs in patients with T1DM who are genetically deficient in glucose-6-phosphate dehydrogenase (G6PD)." (PMID 35242879, 2022).
promyelocytic leukaemia (1 paper, 2016). "Interestingly, depletion of enzymes in oxidative PPP, i.e. G6PD, PGLS (6-phosphogluconolactonase), and PGD, dramatically abrogated the proliferation of HL-60, a human promyelocytic leukaemia cell line." (PMID 27586085, 2016).
pulmonary fibrosis (1 paper, 2022). Chronic progressive interstitial lung disorder characterized by the replacement of the lung tissue by connective tissue, leading to progressive dyspnea, respiratory failure, or right heart failure. "DHEA reduces lung fibrosis and cell proliferation by inducing cell cycle arrest and inhibition of G6PD activity." (PMID 35676709, 2022).
Pv (1 paper, 2015). "However, given Pv’s preference for invading reticulocytes–young red cells with highest levels of G6PD enzyme activity–it is unlikely that a relatively mild G6PD variant (such as G6PDA-, the predominant African variant), would provide any protective advantage against Pv infection." (PMID 26587988, 2015).
Renal cyst (1 paper, 2024). A fluid filled sac in the kidney. "Although the PPP pathway was identified as downregulated, we found that G6PD, encoding the rate-limiting enzyme for the irreversible oxidative phase of the PPP, was upregulated (2.1×) in renal cysts." (PMID 39000280, 2024).
retinal degeneration (1 paper, 2018). Degeneration of the retina. "In the SF and 3HB‐s groups, G6PD activity, Nrf2 level, and expression of the downstream targets of Nrf2 were similar to that in the AL group, consistent with retinal degeneration and metabolomic analysis data." (PMID 29119686, 2018).
sarcopenia (1 paper, 2020). Progressive decline in muscle mass due to aging which results in decreased functional capacity of muscles. "The experimental evidence provides molecular bases for interventions that by increasing the endogenous antioxidant defence (i.e G6PD) will delay the onset of disuse muscle atrophy, sarcopenia, and frailty." (PMID 32371010, 2020).
Seizure (1 paper, 2024). A seizure is an intermittent abnormality of nervous system physiology characterized by a transient occurrence of signs and/or symptoms due to abnormal excessive or synchronous neuronal activity in the brain. "To clarify whether the glucose utilization by the oxidative branch of PPP is involved in the regulation of H2O2 release and epileptiform activity, we analyzed the effects of G6PD inhibition in the 4AP model of epileptic seizures in hippocampal slices." (PMID 38339211, 2024).
selenium deficiency (1 paper, 2023). A nutritional deficiency disease resulting from inadequate selenium levels in the body, which can lead to impaired function of selenoproteins essential for antioxidant defense and thyroid hormone metabolism. "Dietary selenium deficiency may aggravate the oxidative overload in the thyroid gland in G6PD-deficient individuals, thereby increasing the risk of developing AITD." (PMID 36768075, 2023).
serous ovarian cancer (1 paper, 2022). "The upregulation of G6PD, AKR1B1, ITGAV, and TGFβ1 in OVCAR5 CBPR cells was also identified in the tumors of platinum-resistant compared to platinum-sensitive high grade serous ovarian cancer (HGSOC) patients." (PMID 36463238, 2022).
soft tissue sarcoma (1 paper, 2025). A malignant neoplasm arising from muscle tissue, adipose tissue, blood vessels, fibrous tissue, or other supportive tissues excluding the bones. "In efforts to improve existing therapies, we showed that G6PD knockdown increases sensitivity to chemotherapy, a first-line treatment for metastatic MPNSTs and other soft tissue sarcomas." (PMID 40802750, 2025).
staphylococcal infection (1 paper, 2023). An infection caused by Staphylococcus. "We show G6PD deficient patients have globally higher rates of acute infectious diseases, and in particular staphylococcal infections, suggesting a predisposition to infections." (PMID 37753082, 2023). "Staphylococcal infections were particularly more frequent among G6PD deficient patients (OR 1.62, 95% CI 1.14 to 2.27, P<.001)." (PMID 37753082, 2023).
T-cell acute lymphoblastic leukemia (1 paper, 2023). Acute lymphoblastic leukemia of T-cell origin. "Moreover, the mTOR inhibitor, everolimus, was reported to abrogate resistance to dexamethasone in T-cell acute lymphoblastic leukemia cells by reducing G6PD protein levels and enhancing ROS levels." (PMID 37802999, 2023).
thymic lymphoma (1 paper, 2022). "For example, overexpression of G6PD upregulated mRNA expression of NOX gp91phox and p22phox subunits, potentiating ROS production and oxidative damage in mouse pancreatic β cells and thymic lymphoma cells, which provided evidences for NOX-mediated oxidative stress by excess intracellular NADPH." (PMID 38647831, 2022).
tongue cancer (1 paper, 2022). A malignant neoplasm affecting the tongue. "Several pre-clinical studies demonstrated that polydatin exerted therapeutic effects against an orthotopic metastatic tongue cancer model via inhibiting glucose 6 phosphate dehydrogenase (G6PD), and reduced tumor size and lymph node size and metastases." (PMID 36235012, 2022).
tongue squamous cell carcinoma (1 paper, 2024). A squamous cell carcinoma that arises from the tongue. "In human tongue squamous cell carcinoma lines CAL-27 and HSC-3, IL-6 treatment resulted in enhanced nucleotide synthesis and increased G6PD activity, thereby activating the PPP, although G6PD protein expression remained unchanged." (PMID 39796677, 2024).
Torticollis (1 paper, 2015). Involuntary contractions of the neck musculature resulting in an abnormal posture of or abnormal movements of the head. "The birth defects included polydactyly, glucose 6-phosphate dehydrogenase deficiency, hypospadias, ventricular septal defect, cyst of the fourth ventricle of the brain, and torticollis." (PMID 26485575, 2015).
transaldolase deficiency (1 paper, 2024). Transaldolase deficiency is an inborn error of the pentose phosphate pathway that presents in the neonatal or antenatal period with hydrops fetalis, hepatosplenomegaly, hepatic dysfunction, thrombocytopenia, anemia, and renal and cardiac abnormalities. "Branched-chain amino acid catabolism, glucose-6-phosphate dehydrogenase deficiency, ribose-5-phosphate isomerase deficiency, transaldolase deficiency, the valproic acid metabolism pathway, and the valproic acid pathway were found to be significantly impacted (p < 0.05)." (PMID 39061492, 2024).
trypanosomiasis (1 paper, 2014). Infection with protozoa of the genus trypanosoma. "Recent research has shown that steroids may be used to treat trypanosomiasis by inhibiting the glucose-6-phosphate dehydrogenase (G6PD) enzyme in trypanosomes which is the enzyme involved in the first committed step of the pentose-phosphate pathway." (PMID 24862183, 2014).
Zika virus infection (1 paper, 2025). "For example, Zika virus infection induces metabolic reprogramming and reroutes part of the glycolytic carbon flux into PPP, possibly by upregulating G6PD and other key enzymes." (PMID 41204699, 2025).
cancer (375 papers, 2007 to 2026). A tumor composed of atypical neoplastic, often pleomorphic cells that invade other tissues. "Our findings are consistent with previous studies that reported cancer cells with a loss-of-function in G6PD increase flux through ME as a compensatory mechanism to generate NADPH50,51." (PMID 41542490, 2026). "This highlights the need for potential biomarkers of tumor aggressiveness and therapeutic candidates, such as glucose-6-phosphate dehydrogenase (G6PD), whose altered expression has been associated with several cancers." (PMID 41898704, 2026). "Overactive G6PD is associated with the transformation, metastasis, and resistance to therapy in multiple cancer types." (PMID 41124013, 2025). "Recent studies have associated aberrant G6PD activity with critical cancer-related phenomena, such as transformation, metastasis, angiogenesis, and resistance to therapy, in several types of cancer." (PMID 40685383, 2025). "Third, although the biological association between G6PD expression in tumor tissues and cancer progression has been well established, the underlying mechanisms linking serum G6PD activity to tumor progression remain poorly understood." (PMID 41374996, 2025). "G6PD, encoding glucose-6-phosphate dehydrogenase, is a key enzyme in the pentose phosphate pathway and plays an essential role in maintaining redox homeostasis and anabolic metabolism in cancer cells." (PMID 41268553, 2025). "G6PD is usually upregulated in solid tumors and is associated with poor prognosis, making it a potential therapeutic target for cancer." (PMID 40166471, 2025). "On the other hand, by directly reducing glucose‐6‐phosphate dehydrogenase (G6PD) activity, polydatin can prevent tumor development and progression by causing oxidative stress, endoplasmic reticulum stress, and death in cancer cells." (PMID 40190185, 2025). "Gln metabolism and PPP are tightly interconnected: Gln deprivation activates G6PD, whereas a loss of G6PD function activates glutaminolysis in cancer cells." (PMID 39199642, 2024). "G6PD is considered a potential diagnostic marker and has been found to be increased in certain cancers." (PMID 39726786, 2024). "In cancer biology, a higher G6PD expression can cause a higher antioxidant activity in cancer cells and correlate to a poor prognosis in several human cancers." (PMID 39273403, 2024). "Upregulation of G6PD has been observed in various cancer types and is associated with advanced stage, metastasis, invasion, and poor survival outcomes." (PMID 39796677, 2024). "The PPP plays a crucial role in cancer development, with G6PD overexpression linked to the progression of various malignancies." (PMID 39796677, 2024). "Together, these results suggested that high G6PD expression was a risk factor in various cancers and closely related to tumor progression." (PMID 37601657, 2023). "Although upregulation of FASN, GLUD1, and G6PD in the high-risk group barely missed statistical significance, these enzymes deserve attention given their biological significance in cancer and metabolism." (PMID 37760474, 2023). "Earlier studies have observed decreased cancer risk in G6PD deficient patients, in particular for cancers of endodermal origin (colorectal, gastric and liver), but these findings were not replicated in other studies, notably for hematologic malignancies." (PMID 37753082, 2023). "We observed that overall, higher H6PD expression is associated with longer survival, while higher G6PD expression is linked to shorter survival across different types of cancer." (PMID 37867937, 2023). "we observed that there was an association between G6PD expression and six infiltrating immune cells in a majority of tumors, and the top five cancers were KIRC, LGG, LIHC, PAAD, and PRAD." (PMID 37601657, 2023). "G6PD is the most prominent enzyme-linked deficiency whose activity is elevated in different types of cancer." (PMID 37049781, 2023).
cancer (continued). "Acting as an effector of ATM (Ataxia telangiectasia mutated), G6PD often participates in the development of various cancers through metabolic programming and DNA repair pathways." (PMID 38098504, 2023). "G6PD is ubiquitously expressed in mammalian immune cells and the immunological microenvironment is regarded as the “seventh hallmark” of cancer." (PMID 37601657, 2023). "Altogether, these results demonstrated that RIP140 deficiency sensitizes cancer cells to G6PD inhibition." (PMID 35806424, 2022). "Glucose- 6-phosphate dehydrogenase (G6PD) has been recently discovered to be implicated in apoptosis and angiogenesis, making it an excellent target in cancer treatment." (PMID 35991850, 2022). "The rate-limiting enzyme of PPP, G6PD, is regulated by NRF2 and associated with poor prognosis of OSCC, hence, G6PD-targeting limits cancer growth and metastasis by increasing reactive oxygen species (ROS) levels and endoplasmic reticulum stress." (PMID 35327590, 2022). "G6PD is the limiting enzyme of the PPP associated with cancer progression and drug resistance, the inhibition of which indirectly leads to the dysfunction of autophagy." (PMID 36105077, 2022). "G6PD dysregulation has been reported in RCC and various types of human cancers, and elevated levels of G6PD in association with higher levels of PPP-derived metabolites suggests a prominent role of this pathway in RCC-associated metabolic alterations." (PMID 36430837, 2022). "In this review, we will discuss the characteristics of G6PD, roles of G6PD in the development of cancer, inhibitors of G6PD and the mechanisms behind chemotherapy resistance caused by G6PD." (PMID 35207558, 2022). "This is at least partly because loss of G6PD in these cancers leads to compensatory increases in the function of other NADPH-generating enzymes, including malic enzyme and isocitrate dehydrogenase." (PMID 35110412, 2022). "Loss of G6PD in cancer cells generates high NADP, induces compensatory increases in malic enzyme 1 and isocitrate dehydrogenase, and inhibits dihydrofolate reductase activity to block folate-mediated biosynthesis." (PMID 34235071, 2021). "The dual modulation of G6PD on E-Cadherin closely associates glucose metabolism with cancer metastasis." (PMID 32719549, 2020). "In these studies, the oncogenic functions and underlying molecular mechanisms of G6PD in cancer progression have partially been clarified." (PMID 33041664, 2020). "Aberrant activation of G6PD is linked to tumorigenesis and malignancy in rapidly growing cancer cells." (PMID 31500396, 2019). "PPP activity and G6PD itself are often upregulated in cancer and are associated with aggressiveness, drug resistance and poor prognosis." (PMID 30987650, 2019). "Recently our group discovered that the natural molecule polydatin directly inhibits G6PD causing oxidative stress, endoplasmic reticulum stress and apoptosis in cancer cells." (PMID 30987650, 2019). "In studies using dehydroepiandrosterone (DHEA), an inhibitor of G6PD (that is also an adrenal steroid), loss of G6PD function has been suggested to prevent cancer progression." (PMID 30279493, 2018). "The clinical analysis also revealed that the G6PD level is associated with high risk of recurrence and poor survival in patients with gastric and renal cancers." (PMID 29954422, 2018).